ALK (ALK receptor tyrosine kinase)
Diseases named in the same sentence as ALK in open-access papers (continued):
Sharing a sentence is not in itself a finding about the gene and the disease.
tumor (continued). "The clinical phenotype of non-small cell lung cancer (NSCLC) with the fusion gene echinoderm microtubule associated protein like 4 (EML4) - anaplastic lymphoma kinase (ALK), is characterised by early metastasis and poor prognosis in comparison to tumours without a known oncogenic driver." (PMID 32762670, 2020). "A majority of ALK-negative ALCL tumor cells are positive for CD3 and negative for CD15 or PAX5." (PMID 33126356, 2020). "They found that upon doxycycline induction, the anti-ALK svFC-expressing tumors had a significant reduction in tumor size as compared with tumors with no induced expression of the antibody, first demonstrating the therapeutic efficacy of the anti-ALK antibody therapy approach in principle." (PMID 32059449, 2020). "Finally, 72 patients with stage IV were enrolled because of intact data of the detection of ALK rearrangement and serum tumor markers, as well they have not received any previous anticancer therapy." (PMID 31489711, 2020). "For EGFR/ALK negative patients, anti-tumor treatments still rely on the traditional chemotherapy." (PMID 33285759, 2020). "In addition, preferred methods for ALK detection must be suited to formalin‐fixed paraffin‐embedded (FFPE) and biopsy samples because most NSCLC patients are diagnosed in the advanced stage, and tumor tissue is difficult to obtain or limited." (PMID 32543087, 2020). "An average of 53.8% (range 22.3−86.6%) of ALK+ tumor cells, 6% (range 3.5−9.5%) of ALK− tumor cells, 6.8% (range 2.1−11.1%) of adjacent non-tumor cells in ALK+ specimens, and 5.3% (range 0.7−11.2%) of adjacent non-tumor cells in ALK− specimens exhibited positive ALK FISH signal patterns." (PMID 31412611, 2019). "In August 2018, FDA has approved an expanded label for pembrolizumab in combination with pemetrexed and platinum chemotherapy for the first-line treatment of patients with metastatic nonsquamous NSCLC, with no EGFR or ALK genomic tumor aberrations, based on results of the KEYNOTE-189 trial." (PMID 31205619, 2019). "Thus, ALK‐positive NSCLC patients may express fewer neoantigens, possibly leading to an ineffective tumor environment for ICIs." (PMID 31509890, 2019). "Therefore, oncogenic miR-155 displays a very interesting example of microRNA-induced deregulation due to its tumor promoting or repressing functions in both ALK-negative and ALK-positive ALCL, respectively, using different oncogenic mechanisms of action." (PMID 31052302, 2019). "Other ALK-TKI resistance mechanisms can be further classified based on whether or not the tumor is still dependent on ALK signaling (ALK+/ALK−)." (PMID 31815659, 2019). "ALK FISH was tested on one tumor and no gene fusion was detected." (PMID 31712784, 2019). "Atezolizumab, nivolumab, and durvalumab indications are independent of PD-L1 expression, while pembrolizumab is restricted to patients whose tumours do not have EGFR or ALK genomic aberrations and express PD-L1 with a tumour proportion score (TPS) ≥1% determined by an FDA-approved test." (PMID 31262041, 2019). "Therefore, a non-overlapping area of 12% to 21% positivity exists between the ALK+ tumor cells and background noise (up to 11% of positivity obtained from both the ALK− tumor cells and non-tumor cells)." (PMID 31412611, 2019). "In their report, 17 previously tested ALK-positive (ALK+) and 15 ALK-negative (ALK−) NSCLC specimens were thoroughly analyzed to document ALK FISH signal pattern(s) in all types of cells of each specimen, including ALK+ tumor cells, ALK− tumor cells and their adjacent normal areas." (PMID 31412611, 2019). "In fact, due to such technological advances, we have learned that NTRK fusions (and that of orthologues, ROS1, and ALK), irrespective of tumor histology, are more common than previously speculated." (PMID 31551508, 2019). "In our study, we identified only two NSCLC patients with ALK-rearrangements among those with EGFR/KRAS wild-type tumours, so we could not use these data in statistical analyses." (PMID 30953094, 2019).
tumor (continued). "Three tumours with solitary intermediate or positive ALK reaction were also fusion gene-negative." (PMID 31493794, 2019). "In one tumor, with ALK positive reaction, negative nuclear reaction against β-catenin and the lack of CTNNB1 mutation, next generation sequencing revealed a presence of pathogenic variant c.3366_3369del in the APC gene, with homozygous deletion leading to inactivation of both copies in tumor cells." (PMID 30523493, 2019). "Interestingly, in one tumor with the presence of ALK protein expression, neither mutation in exon 3 of the CTNNB1 gene nor nuclear β-catenin immunoreactivity were detected, but the tumor was classified to the WNT group by application of NanoString method." (PMID 30523493, 2019). "During second-line therapy, the biopsied tumour tissue was submitted to fluorescent in situ hybridization analysis (LSI ALK Dual Color Breakapart DNA probe; Vysis®, Abbott Park, IL, U.S.A) that revealed the presence of ALK rearrangement, leading to the initiation of crizotinib 250 mg twice daily." (PMID 29662531, 2018). "However, non-responders were resistant to all ALK inhibitors, despite the presence of ALK rearrangement in FISH-positive circulating tumor cells and circulating free DNA and absence of the ALK inhibitor resistance mutation." (PMID 29844868, 2018). "Therefore, although there was evidence of EMT in rebiopsied tumor samples in the absence of an ALK inhibitor response, administration of additional ALK inhibitors can be effective." (PMID 29844868, 2018). "It is not clear so far whether ALK-specific autoantibodies may act against tumor cells or are merely a surrogate marker for the strength of the patients’ overall cellular immune response against ALCL." (PMID 29642597, 2018). "However, in our experience ALK positive staining, if truly positive, will be found in all (almost all) tumor cells and not merely in a small subpopulation due to its role as driver mutation." (PMID 30466405, 2018). "For the remaining two patients whose tumors were ALK-I19–positive at diagnosis, the residual tumors became ALK-I19 negative, and ALK-negative by IHC and interestingly, most of the cells in these two post-chemotherapy tumor samples showed significant differentiation." (PMID 29535836, 2018). "The fact that “true” ALK negative tumors and normal lung tissue may harbor SS in up to 11% of the tumor cells and ~ 8.5% of the NSCLC show SS between 10 and 15% is further complicating this situation." (PMID 30466405, 2018). "Patients with an identified driver EGFR, ALK or ROS1 should not receive first line ICIs even though tumor cells may express high PD-L1." (PMID 29890761, 2018). "Specifically, our in vitro and in vivo analyses revealed that MIR503HG, which has not been linked to human ALK-negative ALCL, is overexpressed in ALK-negative ALCL cell lines and is significantly upregulated in tumor specimens from mice harboring ALK-negative ALCL tumors." (PMID 29758012, 2018). "FISH and IHC confirmed ALK rearrangement during the first cycle of first-line chemotherapy with a combination of nab-paclitaxel and carboplatin, which did not suppress the rapid growth of the tumor (i.e., PD)." (PMID 29844868, 2018). "Therefore, we aimed to explore the interaction of radiotherapy and ALK-inhibition by TAE684 in tumor cell lines with and without ALK-fusion." (PMID 29304828, 2018). "Furthermore, ALK-specific tumor-reactive T-cells can be detected in the blood of ALK-positive ALCL patients, but not in healthy volunteers." (PMID 29190913, 2017). "Alternatively, this could also be due to specific tumour biology and high sensitivity to ALK inhibition, rather than a direct effect of treatment strategies." (PMID 28423535, 2017).
tumor (continued). "Here we focus on real-world treatment patterns and OS outcomes for people diagnosed with stage IV NSCLC without known EGFR or ALK tumor aberrations in the US community oncology setting during a contemporary time period just before immune checkpoint inhibitors entered standard of care in the US." (PMID 28644837, 2017). "Interestingly, greater PD-L1 expression was observed in IMTs with tumor necrosis and metastasis/recurrence, which were also negative for ALK rearrangement." (PMID 29163763, 2017). "Due to the limited number of reported cases, a lack of awareness of this entity, and significant morphologic and immunophenotypic similarities to other haematopoietic and nonhaematopoietic neoplasms, the diagnosis of ALK+, LBCL may be challenging." (PMID 28665943, 2017). "The aim of this study was to describe overall survival (OS) with current first-line treatment for patients presenting with stage IV NSCLC without known EGFR or ALK tumor aberrations across a broad range of community oncology practices in the United States (US)." (PMID 28644837, 2017). "Third, expression of ALK is largely restricted to tumor tissue rather than healthy adult tissue, which could potentially reduce risk of autoimmunity." (PMID 29190913, 2017). "Moreover, miR-155 silencing results in increased levels of cleaved caspase-3 and SOCS1, which leads to STAT3 signaling suppression and tumor growth reduction in murine models of ALK negative ALCL." (PMID 28061468, 2017). "This patient’s tumor contained an EML4-ALK variant 3a fusion, which has been reported to be relatively resistant to targeted therapy compared to other ALK fusion variants, and failed to respond to both crizotinib and the second-generation ALK inhibitor, ceritinib." (PMID 28763012, 2017). "ALK expression was absent or very low in normal skin; a normalized read count of 0 and 19 in normal skin compared to a mean normalized read count of 4549 (range 71–16,090; >1000 in 22/26) in tumor samples." (PMID 28359267, 2017). "The present case therefore differed with respect to the predictive factors for the presence of the ALK gene fusion in the cavity formation in the tumor, an initial tumor location in a peripheral site without pleural tail formation, and a patient age over 60 years old." (PMID 28321808, 2017). "In conclusion, in this preliminary and exploratory study, we established a plasma microRNA panel that may serve as a novel, non-invasive biomarker for the diagnosis of ALK-positive NSCLC, and may provide considerable value as a predictor of tumor response to treatment with crizotinib." (PMID 28514730, 2017). "ALK copy numbers detected in plasma-derived cfDNA did not correlate (Spearman’s correlation coefficient r = 0.2553) with the copy number determined using tumor gDNA." (PMID 29156716, 2017). "Interestingly, patient number 36 presented with an EML4-ALK fusion based on PCR data, but FISH indicated that this patient was ALK rearrangement-negative since there were very few ALK rearrangement-positive cells (approximately 3%) in the tumor." (PMID 28032602, 2017). "A female showed ALK rearrangement in the primary tumor (17 % break-apart signals) on FISH, but was negative in the metastatic brain tumor (FISH: 1 %); interestingly, KRAS testing led to the opposite result: detection of the G12C mutation in the metastatic but not in the primary lesion." (PMID 26968843, 2016). "However, no-rearrangements-positive signal patterns were observed for the cells collected from the ALK negative patient and its primary tumor counterpart." (PMID 27739521, 2016). "Regarding our immunohistochemical studies, we would like to point out that, while we found only ~30% of tumor cells being labeled with MYC, two previous publications showed that MYC immunohistochemical reactivity is detectable in the majority of tumor cells in ALK + ALCL." (PMID 27821172, 2016).
tumor (continued). "In this case, expression of EMA, clusterin, or CD56 in tumor cells may help to support a diagnosis of ALK negative ALCL, as the staining of these markers are known to be absent in HL." (PMID 27612448, 2016). "We also found that ALK-positive patients tended to have smaller tumors (≤ 3 cm) compared to those in EGFR-positive patients, suggesting that genomic state could influence the tumor size." (PMID 27518729, 2016). "Genomic analysis revealed neither an ALK gene rearrangement nor EGFR, BRAF or HER2 gene mutations, but an activating point mutation of the KRAS gene (p.G12C, exon 2) and therefore this tumor could be considered a non-responder case to EGFR-TKI therapy." (PMID 27548442, 2016). "However, ALK positive DLBCL constantly lack the expression of CD30 in immunohistochemistry, and strongly express plasma cell markers such as CD138 and CD38, which demonstrates the features of terminally differentiated B-lineage origin of the tumor cells." (PMID 27612448, 2016). "Currently, however ROS1 testing is often part of a second phase of testing in a patient whose tumour is negative for more common, routinely tested alterations such as EGFR and KRAS mutation and ALK gene rearrangement and who is a lifelong never or long-time ex-smoker." (PMID 27535289, 2016). "This illustrates the clonal evolution of lung tumors and the fact that ALK-positive clones sampled by biopsy may not necessarily be representative of the entire tumor." (PMID 26968843, 2016). "We reasoned that a comprehensive study of the ALCL methylome might help to elucidate the impact of ALK-specific signaling on the epigenome of ALK+ ALCL in relation to ALK− ALCL and allow for a better classification of ALCL tumor cells with regard to their cellular origin." (PMID 27705804, 2016). "The tumor did not harbor either EGFR or, KRAS mutations or ALK rearrangement." (PMID 27150058, 2016). "Additionally, never-smoker, anaplastic lymphoma kinase (ALK) gene rearrangement, low tumor TS RNA level, thyroid transcription factor-1 (TTF-1) expression and low serum leptin level were associated with a good response to pemetrexed in previous studies." (PMID 27388008, 2016). "Similar, crizotinib can be administered to patients with ROS1-rearranged NSCLC that do not express ALK or c-Met, as LDK378 (Ceritinib) and AP26113 ALK inhibitors demonstrate clinical efficacy on crizotinib-resistant NSCLC tumours with increased abundance of IGF-1R and ROS proteins." (PMID 26147305, 2015). "However, little is known about the molecular features and tumour drivers in ALK-negative ALCL (ALCL ALK−), which is characterized by a worse prognosis." (PMID 25820993, 2015). "Furthermore, 9 out of 10 ALK-rearranged sample cases showed the rearrangements in the solid component regardless of the other subtypes within the tumor." (PMID 26422230, 2015). "The other tumor subtypes were not relevant to ALK CNG status in this study." (PMID 25803816, 2015). "The strategies described here could also benefit patients with ALK-translocated cancers, where the F1174L mutation modulates crizotinib resistance and the same signaling pathways that drive tumor cells without translocated ALK are active." (PMID 25228590, 2014). "Of the 77 ALK-negative NSCLCs, 21 specimens were excluded for lack of tumor tissue." (PMID 25248157, 2014). "The results of our study indicate that the overexpression of wild-type ALK alone may not be sufficient to drive tumor growth and that ALK may therefore not be an effective drug target in RMS." (PMID 24406431, 2014). "Staining for AE1/AE3, S-100, smooth muscle actin (SMA), desmin, cluster of differentiation 31 (CD31), CD34 and anaplastic lymphoma receptor tyrosine kinase (ALK) was negative, while the staining for vimentin was strongly positive (+++) with >50% positive tumor cells." (PMID 24959221, 2014).
tumor (continued). "Regardless of whether or not GzB expression is prognostic or predictive of ALK+ ALCL outcome, our results clearly demonstrate that it is a factor contributing to the susceptibility of these tumour cells to drug-induced apoptosis." (PMID 25168906, 2014). "Immunohistochemistry staining was negative in the tumor with ALK FISH positive test." (PMID 25083769, 2014). "In addition, only ALK fusion-negative tumours showed an increase of the frequency of chromosome arm gain with the advancement of disease stage." (PMID 23289484, 2013). "Note that in ALK fusion-positive tumours, genomic copy number changes were more evenly distributed over the chromosome arms and high copy number gains (dark-red) in short genomic segments were less frequently encountered than with ALK-fusion negative examples." (PMID 23289484, 2013). "Among the 20 IHC-positive cases, 15 cases were confirmed as ALK rearrangement by ALK FISH, 5 cases were not interpretable, due to the technical artifacts such as signal loss that possibly resulted from inappropriate fixation or loss of tumor tissue." (PMID 23741400, 2013). "Analysis of five LADC cases of never-smokers without EGFR/KRAS/ALK alterations using transcriptome sequencing identified 56 reads overriding the in-frame EZR-ROS1 gene fusion point connecting EZR exon 10 to ROS1 exon 34 in one tumor." (PMID 23418494, 2013). "All the ALK-positive cases exhibited a diffuse and cytoplasmic staining pattern in tumor cells, and no immunostaining was observed in normal lung bronchial epithelium, alveolar pneumocytes, alveolar macrophages, mesenchymal tissue, and inflammatory cells in the adjacent lung tissues." (PMID 23741400, 2013). "Unlike other scoring systems for anti-ALK IHC, staining intensity, which may be a less objective indicator than positive tumor cell rate, is not basically considered in iScore, except for the cases showing “checker board pattern”." (PMID 23936355, 2013). "Applying this methodology, we demonstrated that lung adenocarcnomas with ALK fusion feature less amplification of loci with oncogenes and fewer deletions of loci related to tumour suppressor genes, although global chromosome aberrations were similar between tumours with and without ALK fusion." (PMID 23289484, 2013). "Although the size of tumor was smaller (P = 0.034), ALK-positive adenocarcinoma showed more aggressive biological characteristics compared to ALK-negative adenocarcinoma: more advanced stage disease (P = 0.014) and more frequent lymph node involvement (P = 0.002)." (PMID 23936355, 2013). "It will be therefore interesting to investigate how GAPDH could contribute with FDG uptake level and tumor stage in building a composite prognostic marker, possibly also correlating it with the status of known NSCLC oncogenic genes (PI3K, EGFR, KRAS, ALK, etc.)." (PMID 23988223, 2013). "At low-power microscopy, the tumor was homogeneously stained positive for ALK (data not shown)." (PMID 23617234, 2013). "All patients with ALK FISH negative tumours were negative for ALK IHC." (PMID 23359795, 2013). "All 30 primary tumor samples were negative for ALK protein overexpression." (PMID 24156086, 2013). "In addition, EML4–ALK was identified by using fluorescent in situ hybridization (FISH) for ALK rearrangements and was confirmed by immunohistochemistry for ALK expression in tumor." (PMID 23714228, 2013). "Tumor size was not significantly different between ALK-rearranged and ALK-negative tumors." (PMID 24194854, 2013). "Our case also demonstrates that NSAID therapy may be successful in a non-ALK rearranged tumor in which ALK inhibition is not an option." (PMID 23761833, 2013). "This indicated that a tumor that is positively immunostained for ALK only by a sensitive immunohistochemistry method but not by conventional methods may harbor a novel ALK fusion." (PMID 22347464, 2012).